FAM222B (family with sequence similarity 222 member B)
Synonyms: C17orf63; FLJ10700
Tractability: PROTAC: ubiquitination databases record sites on it.
Gene: Protein-coding gene on chromosome 17 (28,755,971 to 28,855,232, reverse strand). Ensembl gene ENSG00000173065.
Subcellular location (Human Protein Atlas): Nucleoplasm
Gene Ontology:
Molecular function: protein binding
Cellular component: mitochondrion; nucleoplasm
Genetic constraint (gnomAD): Loss-of-function variants: 12 observed, 36.28 expected, observed/expected ratio (o/e) 0.33, 90% interval 0.21 to 0.54. The upper end of that interval is the gene's LOEUF score, 0.54, which puts it in group 2 of 6, group 1 being the genes least tolerant of losing a copy. Missense variants: 716 observed, 743.86 expected, observed/expected ratio (o/e) 0.96, 90% interval 0.9 to 1.02. Synonymous variants: 329 observed, 315.51 expected, observed/expected ratio (o/e) 1.04, 90% interval 0.95 to 1.14.
Homologues: Orthologues: chimpanzee FAM222B (100% identical), macaque FAM222B (99% identical), dog FAM222B (98% identical), rat Fam222b (98% identical), mouse Fam222b (97% identical), pig FAM222B (97% identical), rabbit FAM222B (97% identical), guinea pig FAM222B (96% identical), tropical clawed frog fam222b (73% identical), zebrafish fam222bb (59% identical), zebrafish fam222ba (52% identical). Paralogues in human: FAM222A (26% identical).
Diseases named in the same sentence as FAM222B in open-access papers:
FAM222B is named in the same sentence as 1 disease in open-access papers, as found by Europe PMC text mining. Sharing a sentence is not in itself a finding about the gene and the disease.
FAM222B shares sentences with these, for which no sentence is quoted: cancer (1 paper).